ELN (elastin)
Diseases named in the same sentence as ELN in open-access papers (continued):
Sharing a sentence is not in itself a finding about the gene and the disease.
aortic aneurysm (continued). "In addition to disorganized elastin fibers, Ang II-infusion also induced significant medial degeneration resulting in decreased thoracic aortic media thickness, a clinical feature commonly observed in patients with aortic aneurysms." (PMID 36555207, 2022). "Hence, the finding of only moderately decreased medial fraction of elastin in aortic aneurysms may have been skewed by including subjects with bicuspid aortic valves." (PMID 34162971, 2021). "In this context, elastin-specific molecular MRI could not only quantify the elastin content in arteriosclerotic plaques on the basis of signal intensity, but also predict potential rupture sites in the course of an aortic aneurysm in follow-up studies." (PMID 33247185, 2020). "The less severe elastin degradation of the aortic aneurysm aorta may be attenuated by MMP activity." (PMID 32064021, 2020). "The shared molecular pathways of elastin degradation, SMC apoptosis, and inflammatory responses provide a strong foundation for adapting the nanoparticle-based therapies developed for aortic aneurysms to treat cerebral aneurysms." (PMID 39595942, 2024). "Regulation of elastin (ELN) by hsa-miR-195-5p has not been reported before in the context of XFG but was experimentally demonstrated in aortic aneurysmal disease." (PMID 39883689, 2025). "Similarly, in aortic aneurysm and dissection models, suppressing the expression of NLRP3 inflammasome components while simultaneously enhancing elastin protein expression has been observed." (PMID 38992615, 2024). "Doxycycline has been widely studied for its potential in treating aortic aneurysms due to its ability to inhibit the expression of MMPs, particularly MMP-2 and MMP-9, which are key enzymes involved in the degradation of elastin and collagen in the aneurysmal wall." (PMID 39595942, 2024). "Elastin is a crucial structural component of the aorta, and its degradation by proteolytic enzymes such as matrix metalloproteinases (MMP) contributes to the development of aortic aneurysm." (PMID 34428207, 2021). "Although, the importance of disordered elastin turnover in aortic aneurysm/dissection is well established,21–23,48in vivo detection of dysfunctional elastin remodelling has been hampered by the lack of a clinically validated, non-invasive diagnostic tool." (PMID 31282949, 2020). "Perturbation of normal elastin laminar structure may arise from induction of TGFβ regulated matrix metalloproteinases (MMP), a family of endopeptidases responsible for the degradation of the extracellular matrix in aortic aneurysms." (PMID 24587008, 2014). "Notably, local IL-1β might participate in the formation of aortic dissecting aneurysms by promoting extracellular matrix (ECM) metalloproteinase (MMP)-2 and MMP-9 and the breakage of elastin fibers, thus weakening the biomechanical properties of the aortic wall." (PMID 33460398, 2021). "However, a propensity for aortic aneurysm formation has not been demonstrated in ELN mutant mice." (PMID 28116311, 2017).
Williams-Beuren syndrome (64 papers, 2008 to 2026). "Patients with mutations restricted to the ELN gene exhibit cardiovascular abnormalities similar to those in Williams syndrome but lack among others the syndrome's characteristic facial features." (PMID 41292695, 2025). "Just as in Williams syndrome, patients carrying loss-of-function mutations confined to ELN often present with SVAS, thickened aortic walls, and reduced aortic lumina." (PMID 41292695, 2025). "Structural abnormalities of the cardiovascular system in Williams syndrome have been attributed to the hemizygous loss of the elastin (ELN) gene." (PMID 41292695, 2025). "Williams syndrome is a genetic abnormality associated with elastin gene, and diverticulosis is reported to be identified as high as 18% in the pediatric cohort." (PMID 40520836, 2025). "Williams syndrome (WS) is a rare genetic disorder caused by a microdeletion at chromosome 7q11.23, affecting 26–28 genes, including ELN, which is essential for elastin production." (PMID 41226524, 2025). "Williams syndrome (WS) is a structural chromosomal abnormality caused by a deletion in the 7q11.23 band involving the elastin gene (ELN) and is a rare genetic disease associated with congenital heart disease." (PMID 39768857, 2024). "Reduction of elastin synthesis by VSMCs in Williams Beuren Syndrome and supravalvular aortic stenosis is associated with dysregulation of MMP-9/tissue inhibitor of metalloproteinase-1 (TIMP-1) leading to enhanced elastolytic capability." (PMID 37001705, 2023). "Williams’ syndrome results from mutations that include the elastin gene; it is characterized by supravalvular aortic stenosis (SVAS), that is, marked narrowing of the proximal aorta." (PMID 36315608, 2022). "ELN gene mutations are thought to be responsible for the vascular and connective tissue impairments in William’s syndrome that are also associated with excess adipose deposition." (PMID 35743063, 2022). "Williams Beuren syndrome, non-syndromic supravalvular aortic stenosis, and the autosomal dominant cutis laxa are all consequences of mutations in the ELN gene." (PMID 35216218, 2022). "A recurrent deletion of 7q11.23 that results in loss of ELN causes Williams syndrome, while heterozygous loss-of-function ELN variants are associated with a rare (1/20,000) familial SVAS." (PMID 35737725, 2022). "Mutations in the ELN gene, encoding elastin (ELN), result in Williams Syndrome, a syndrome characterized by supravalvar aortic stenosis, cutis laxa, and other disorders of connective tissue." (PMID 28116311, 2017). "Williams-Beuren syndrome (WBS) is a rare multisystem disorder caused by a hemizygous deletion of the elastin gene on chromosome 7q11.23." (PMID 28744380, 2017). "Such iPSCs have been obtained from a patient having 4-nucleotide insertion in ELN causing a frameshift mutation and premature transcription termination in exon 10 and from Williams-Beuren syndrome patients." (PMID 27110425, 2016). "Williams Beuren syndrome is a rare neurodevelopmental genetic disorder caused in majority of cases by a microdeletion of ELN gene that encodes for elastin." (PMID 25722758, 2014). "Given that Williams Beuren Syndrome chiefly reduces tropoelastin synthesis and autosomal dominant cutis laxa mutations produce altered tropoelastin protein, this is likely a key factor in the differential manifestation of elastin related disease." (PMID 37001705, 2023). "Williams syndrome is caused by a deletion of the elastin gene on chromosome 7." (PMID 35936144, 2022). "The genetic origins of William’s syndrome involve the ELN gene that encodes for elastin." (PMID 35743063, 2022). "The Williams-Beuren syndrome (WBS) is a complex multisystemic developmental disorder caused by hemizygous microdeletion around the elastin gene on chromosome 7." (PMID 23675084, 2008). "Both most prevalent forms of Williams syndrome include ELN deletion, but NCF1 is only affected in the longer deletion." (PMID 41292695, 2025).
Williams-Beuren syndrome (continued). "The ELN gene can be causative for cutis laxa or supravalvular aortic stenosis typical of the Williams syndrome due to chromosome 7q11.23 deletion including ELN." (PMID 41010011, 2025). "It is generally assumed that haploinsufficiency of ELN is the main culprit for the vascular phenotype in Williams syndrome." (PMID 41292695, 2025). "The elastin ELN gene is the most important in the Williams syndrome microdeletion syndrome deleted region." (PMID 39493104, 2024). "In Williams-Beuren syndrome, impairment of the elastin ELN gene results in four out of five patients having cardiovascular abnormalities, with mutations also resulting in congenital heart disease." (PMID 37498175, 2023). "Williams-Beuren syndrome is a rare genetic disease (1/20 000) characterized by a microdeletion at 7q11.23 encompassing about 28 genes, including the elastin gene, ELN." (PMID 38405095, 2023). "Seemingly contradictory, while both Eln +/− mice and William’s Beuren Syndrome have reduced total elastin content, there is an increased number of elastic lamellae observed outside regions of stenosis." (PMID 37001705, 2023). "SVPS is considered secondary to an elastin arteriopathy, such as observed in clinical entities consistent with Williams’ syndrome." (PMID 37240210, 2023). "In autosomal dominant cutis laxa, dermal elastin is also degraded, with presentation typically being more severe than Williams Beuren Syndrome." (PMID 37001705, 2023). "Williams’ syndrome has been studied using different animal models, including the Eln+/- mouse, which produces about 50% of the normal elastin." (PMID 36315608, 2022). "In Williams syndrome (WS) patients, a 500 kb region at 7q11.23 containing ELN and other genes is deleted, suggesting the important role of tropoelastin in the aetiology of WS." (PMID 35456902, 2022). "Familial autosomal dominant SVAS is frequently associated with elastin (ELN) gene mutations, whereas Williams-Beuren syndrome is a complex developmental disorder caused by heterozygous microdeletions of 26–28 genes at 7q11.23, including ELN." (PMID 36518217, 2022). "Some diseases are directly linked to a mutation in the ELN gene in human, such as Williams Beuren syndrome (WBS, also called Williams syndrome), non-syndromic supravalvular aortic stenosis (SVAS), or the autosomal dominant cutis laxa (ADCL)." (PMID 35216218, 2022). "Williams Beuren syndrome (WBS) is a recurrent microdeletion disorder that removes one copy of elastin (ELN), resulting in large artery vasculopathy." (PMID 35665242, 2022). "One of the characteristic features of elastin insufficiency is large artery stiffness assessed by pressure-diameter curves experimentally in Eln+/− mice and by pulse wave velocity in humans with Williams syndrome." (PMID 34790711, 2021). "SAS is caused by heterozygous mutations in ELN or deletions in the q-arm of chromosome 7 (7q11.23, Williams-Beuren syndrome) which also involve ELN." (PMID 27110425, 2016). "The FISH generated one ELN signal in 20 metaphases read and found the presence of ELN deletion, with compatible Williams-Beuren syndrome." (PMID 26958139, 2015). "The FISH generated one ELN signal in 20 metaphases read and found the presence of deletion of ELN locus, compatible with Williams-Beuren syndrome." (PMID 26958139, 2015). "Williams-Beuren syndrome is the consequence of a large contiguous-gene deletion on the seventh human chromosome that includes the elastin gene." (PMID 26167199, 2014). "Microdeletions of the region on 7q11, encompassing the ELN gene, result in Williams-Beuren syndrome (WBS, OMIM #194050)." (PMID 23442826, 2013). "Fluorescent in situ hybridization (FISH) was performed and the result was: 46.XX, ish del (7q11.2) (ELN X1) (7q22 X2) ELN deletion compatible with Williams syndrome." (PMID 22927862, 2012).
Williams-Beuren syndrome (continued). "Major defects in the elastin gene (ELN) are associated with a number of disorders including Supravalvular aortic stenosis (SVAS), Williams-Beuren syndrome (WBS) and autosomal dominant cutis laxa (ADCL)." (PMID 23049958, 2012). "Mutations within the elastin gene have also been found in patients with isolated supravalvar aortic stenosis, and deletion of the elastin gene in patients with Williams' syndrome is thought to account for the cardiovascular phenotype." (PMID 22927862, 2012). "Fluorescent in situ hybridization was performed, and the result was 46.XX, ish del (7q11.2) (ELN X1) (7q22 X2) ELN deletion compatible with Williams' syndrome." (PMID 22927862, 2012). "Patients with Williams syndrome have elastin gene deletions which result in altered deposition of elastic fibres in the skin and a subclinical dermal phenotype." (PMID 19128471, 2009). "The STS database at the NCI/NCBI GenBank was searched for unique sequences that are present around the elastin gene in the Williams-Beuren syndrome critical region (WBSCR) on human chromosome 7." (PMID 23675084, 2008). "We used it to map hemizygous microdeletion on human chromosome 7 around the elastin gene (ELN), which is the molecular basis of the Williams-Beuren syndrome (WBS)." (PMID 23675084, 2008). "The diagnosis of Williams syndrome can be confirmed or excluded by FISH studies targeting the elastin (ELN) gene at 7q11.2, just as appropriate laboratory studies can detect deletion 22q13." (PMID 18505557, 2008). "Williams syndrome, a developmental disorder resulting from deletions on chromosome 7q11.23 encompassing the elastin (ELN) gene, displays characteristic dysmorphic features and pronounced variability in facial musculature, impacting muscles including ZMa and ZMi." (PMID 40565856, 2025). "Notably, according to the ClinGen database, this duplicated chromosome segment completely overlaps with the 7q11.23 recurrent (Williams-Beuren syndrome) region (including ELN), indicating an established triplosensitive (TS) effect." (PMID 39108315, 2024). "Furthermore, William’s Beuren Syndrome and autosomal dominant cutis laxa, VSMCs have a greater proliferative capacity with reduced elastin secretion and deposition." (PMID 37001705, 2023). "Using a combination of gene-targeted mice, tissues and cells from patients with Williams-Beuren syndrome, and targeting of elastin in human VSMCs, the authors identified VSMC-derived NOTCH3 signaling as a critical mediator of aortic hypermuscularization and loss of vascular patency." (PMID 35229725, 2022). "Insoluble elastin also functions to regulate vascular smooth muscle cell proliferation, with a functional haploinsufficiency of ELN causing the Mendelian disease Williams-Beuren syndrome, which is characterised by supravalvular aortic stenosis amongst other systemic features." (PMID 35922433, 2022). "Moreover, all patients were found to have a common deletion in the Williams-Beuren syndrome chromosome region at the 7q11.23 locus, which contained the elastin gene." (PMID 35765027, 2022). "Smoking, of course, should be discouraged in all individuals, but avoidance may be even more important in people with elastin insufficiency—both those with Williams syndrome and those with familial ELN-related SVAS." (PMID 35741248, 2022). "Gain-of-function mutations in ELN lead to ADCL, whereas loss-of-function point mutations or contiguous gene deletions (involving ELN) give rise to isolated supravalvular aortic stenosis and Williams-Beuren syndrome, respectively." (PMID 22801769, 2013). "The biological roles of elastin vary between tissues: controlling proliferation of vascular smooth muscle and stabilizing arterial structure; mediating disease states of Supravalvular aortic stenosis and Williams syndrome." (PMID 24058543, 2013). "Indeed, patients with loss-of-function mutations in ELN develop elastin arteriopathy, but not the craniofacial or neurological symptoms of Williams syndrome." (PMID 41292695, 2025).
Williams-Beuren syndrome (continued). "Known genetic diseases associated with elastin include the haploinsufficiency disorders, supravalvular aortic stenosis (SVAS) and Williams-Beuren syndrome (WBS), with cardiovascular consequences." (PMID 23049958, 2012). "Thus, despite the overlap in vascular deficits between isolated ELN loss-of-function mutations and Williams syndrome, the symptoms are not identical, indicating that other genes in the WSCR may modulate the phenotype." (PMID 41292695, 2025). "ASD0027 carried a de novo duplication of the 7q11.23 recurrent region (Williams-Beuren syndrome, OMIM #609757, including the ELN gene)." (PMID 37035742, 2023). "Hemizygosity of the elastin gene (ELN) is seen in over 90% of cases and has been demonstrated to be responsible for the vascular and connective tissue defects in Williams syndrome." (PMID 33990852, 2022). "In fact, people with the Williams-Beuren syndrome (OMIM 194050), who lack 1.5 million base pairs at 7q11.23 encompassing at least 17 genes, including the tropoelastin gene (ELN), can also present with lipedema-like tissue." (PMID 33786515, 2020). "Even though there is no direct link with VKDP and VKCFD1, this disease is caused by a deletion of the WBSCR (Williams–Beuren syndrome critical region), including the ELN gene (elastin; OMIM*130160), responsible for the arteriopathy in Williams-Beuren syndrome." (PMID 28125048, 2017). "In the mentioned affected family, first step screening revealed deletion of ELN and LIMK1 genes in an 8-year old ID patient, suggestive of Williams-Beuren Syndrome." (PMID 22283845, 2012). "In addition to the single gene defects, elastin-mediated disease also occurs through a contiguous deletion on human chromosome 7q11.23 that removes 25–27 genes, including ELN: Williams syndrome (Williams–Beuren syndrome, WS, MIM #194050)." (PMID 35741248, 2022). "In humans, heterozygous elastin deletions are, by contrast, not lethal, but cause severe supravalvular aortic stenosis (SVAS) or Williams-Beuren syndrome (WBS; omim.org)." (PMID 33317537, 2020).